SNAI1 (snail family transcriptional repressor 1)
Diseases named in the same sentence as SNAI1 in open-access papers (continued):
Sharing a sentence is not in itself a finding about the gene and the disease.
pancreatic cancer (75 papers, 2010 to 2026). "In our study, we also noticed that dysregulation of miR-30a along with SNAI1 was associated with poor prognosis in pancreatic cancer." (PMID 30770779, 2019). "Our data supports the idea that overexpression of SNAI1 may be associated with more invasive features of the pancreatic cancer resulting in peripancreatic invasion." (PMID 41481650, 2026). "Our study emphasizes the critical impact of ZEB1 and SNAI1 overexpression on survival rates in pancreatic cancer, primarily due to their roles in facilitating peripancreatic invasion." (PMID 41481650, 2026). "The metastasis of pancreatic cancer is associated with colon cancer protein 1 (MACC1), which positively interacts with SNAI1; this interaction represses CDH1 (which encodes E-cadherin) and enhances fibronectin 1 (FN1) expression, which promotes cell migration." (PMID 39941895, 2025). "For example, BMP-4 induces the expression of the EMT-associated transcription factors SNAI1 and SNAI2, which encode Snail and Slug, respectively, in a Smad4-dependent manner in ovarian and pancreatic cancer cells." (PMID 35693928, 2022). "In pancreatic cancer, HuR can bind to the SNAI1 mRNA and upregulation its expression to promote metastasis of tumor." (PMID 36071042, 2022). "RING1A/1B was reported to interact with SNAI1, another EMT-TF, and contribute to SNAI1-mediated repression of CDH1 in pancreatic cancer cells." (PMID 33779563, 2021). "The gene expression analysis of EMT markers Zeb1, Vimentin, and Col1a1 were significantly decreased in YFP sorted primary pancreatic cancer cell lines from KPC;ST mice, along with complete loss of Snai1 and Twist1." (PMID 33852841, 2021). "According to the literature, the expression of the FAP, CXCL12, CTGF, and SNAI1 genes is characteristic of CAFs in the TME of pancreatic cancer." (PMID 33804861, 2021). "In contrast, TWIST and SNAIL dampen the response to gemcitabine in an autochthonous mouse model of pancreatic cancer as Snai1 and Twist1 knockout results in prolonged survival in gemcitabine‐treated tumor mice." (PMID 34459003, 2021). "K-Ras pancreatic cancers with active TGF-β pathways (50%) upregulate the Snail family transcriptional repressor 1 (SNAIL), thus repressing KLF5 expression and, in parallel, activating AKT switch ID1 regulation by TGF-β from repression into induction." (PMID 32516941, 2020). "To confirm it, we compared the expression levels of miR-30a and SNAI1 in pancreatic cancer patient tissue and normal tissues samples." (PMID 30770779, 2019). "We also examined the direct effect of SNAI1 ablation on pancreatic cancer cell response to gemcitabine." (PMID 30770779, 2019). "Our data suggested that GATA6-AS1 can inhibit PDAC cell proliferation, invasion, migration, EMT process and metastasis under hypoxia, and disrupting the GATA6-AS1/FTO/SNAI1 axis might be a viable therapeutic approach for refractory hypoxic pancreatic cancers." (PMID 38057853, 2023). "Furthermore, we validated several miRNAs nodes that have been dysregulated during gemcitabine resistance, and subsequently confirmed the role of miR-30a in pancreatic cancer cell sensitization to chemotherapy, mainly through SNAI1/IRS1/ERK/AKT pathway." (PMID 30770779, 2019). "Similarly, a SMO knockdown human pancreatic cancer stem cell demonstrated a decrease in the expression of E-cadherin and increase in the expression of SNAI1 and N-cadherin." (PMID 31547193, 2019). "Moreover, miR-30a also appeared to enhance gemcitabine response in vivo, thereby implicating miR-30a-SNAI1 axis as potential treatment option for pancreatic cancers." (PMID 30770779, 2019). "Based on the study of TRIM50 in liver and pancreatic cancer, it was found that TRIM50 blocked EMT by targeting SNAI1 and down-regulating its expression." (PMID 39538371, 2024). "Mouse Cldn4 is downregulated in EMT in response to SNAI1 and expression of CLDN4 decreases the potential of pancreatic cancer cells to metastasize downstream of both MEK and PI3K." (PMID 20844758, 2010).
pancreatic cancer (continued). "Additionally, we observed that ZEB1 overexpression is contingent upon the overexpression of SNAI1, indicating a regulatory cascade where SNAI1 enhances the expression of ZEB1, further promoting invasive and metastatic behavior of pancreatic cancer cells." (PMID 41481650, 2026). "The comparison of EMT-TFs expression levels between PDAC and healthy pancreatic tissue revealed significantly elevated mRNA levels of SNAI1, SNAI2, ZEB1 and TWIST in pancreatic cancer tissue, while ZEB2 expression was higher in normal pancreatic tissue (p < 0.05)." (PMID 41481650, 2026). "Part of these genes have been reported in basic studies of pancreatic cancer and are closely related to the invasion and metastasis of pancreatic cancer according to the literature, including MYC, CDH2, SNAI1, YAP1, SOX2." (PMID 35237592, 2022). "Oncostatin M may induce the expression of Zeb1 and Snail (SNAI1), thereby regulating an EMT program conferring resistance to gemcitabine in pancreatic cancer." (PMID 36497409, 2022). "Very strikingly, in pancreatic cancer, TGFβ‐mediated EMT depends almost exclusively on ZEB1, since Zeb1 knockout in KPC cells blocks more than 90% of TGFβ‐induced alterations in gene expression, despite of Snai1 upregulation during TGFβ treatment." (PMID 34459003, 2021). "In this regard, Snai1 and Twist1 may indeed be dispensable for metastatic progression of PDAC, but the critical role of the EMT activator Zeb1 in this cancer type means that we cannot dismiss EMT as a fundamental event preceding invasion and metastasis of pancreatic cancer." (PMID 29903049, 2018).
colon carcinoma (71 papers, 2005 to 2025). "In co-xenografted nude mice, the expression of SNAI1 in stromal fibroblasts was required for the pro-tumorigenic effect of these cells on colon cancer growth and invasion." (PMID 34768901, 2021). "For instance, in colon cancer cells, the SNAI1 promoter is regulated by phosphorylated p68 RNA helicase, which induces the dissociation of the HDAC1 from the SNAI1 promoter and activates its transcription." (PMID 31141910, 2019). "It has been shown in the colon cancer cell line HT-29-M6 that both SNAI1 and EZH2 were required to recruit PRC2 on the promoter of CDH1, and that EZH2 and SNAI1 stabilized each other on this promoter." (PMID 34991274, 2018). "The results of our study are relevant for the clinic, as VDR expression is downregulated in approximately two-thirds of advanced colon tumors associated to the upregulation of SNAI1 and SNAI2 genes that code for SNAIL1/SNAIL2 transcriptional repressors." (PMID 21858154, 2011). "Moreover, EMT is activated by ZNF281 in colon cancer cells through the regulation of SNAI1 and other EMT-related gene expressions." (PMID 39518154, 2024). "Indeed, in colon cancer, SNAIL1 (also known as SNAI1) is capable of fine-tuning Wnt/β-catenin signalling to promote invasion and proliferation." (PMID 36621522, 2023). "The expression of SNAI1 protein, the main inducer of EMT, has been detected at the tumor–stromal interface in colon cancer and elevated endogenous levels of SNAI1 in cancer cells have been shown to increase tumor initiation capacity and metastatic potential in mouse and human models." (PMID 33806312, 2021). "A recent study showed that a histone deacetylase inhibitor, trichostatin A, which induces SNAI1 and SNAI2 expression, inhibits SLC2A5/GLUT5 expression and thereby sensitizes colon cancer cells to cisplatin and oxaliplatin." (PMID 39458997, 2024). "The expression of the third family member, Snail/SNAI1 itself, has also been shown to correlate with the expression of TUBB3/βIII-tubulin in colon cancer cells, however other than expression, no mechanistic study has been reported." (PMID 35573698, 2022). "Zinc finger protein SNAI1 (SNAIL) family members are activators of EMT and are highly expressed by CRC colonospheres containing colon cancer stem cells." (PMID 35791509, 2022). "Supporting this, VDR RNA expression correlates directly with differentiation and inversely with SNAI1 and SNAI2 RNA expression in human colon tumors." (PMID 32854355, 2020). "Upon treatment with IL-6, the 2 colon cancer cell lines showed decreased levels of E-cadherin and increased levels of phosphorylated STAT3, N-cadherin, SNAI1, and vimentin." (PMID 30308035, 2018). "Third, we finally analyzed the expression of transcription factors known to be mediators of EMT in colon cancer cells, namely ZEB1, SNAI1 (also known as Snail), SNAI2 (also known as Slug), and TWIST." (PMID 29462209, 2018). "c-Myc, Snai1, and Id1, but not Tcf4 and Id2, were found to be highly expressed in the colon cancer cell-derived CM-treated group compared to the control (Ctrl) group." (PMID 37996458, 2023). "We found that the expression of ZEB1, SNAI1 and SNAI2 were clearly induced in the two colon cancer cell lines by MACRO-CM from U937 macrophages, with the exception of HT-29 cells that did not expressed detectable levels of SNAI2 mRNA under any culture condition." (PMID 29462209, 2018). "Similarly, differential expression of some transcription factors involved in epithelial-to-mesenchymal transitions (i.e. ZEB1, SNAI1, and SNAI2) was variably observed in the colon cancer cell lines when exposed to the inflammatory media." (PMID 29462209, 2018). "Except for the heterozygous deletion of TWIST1 and SNAI1 in CRC, and the lack of SIX2 in colon cancer, all other genes have heterozygous deletions." (PMID 34526059, 2021).
prostate carcinoma (64 papers, 2011 to 2025). A carcinoma that arises from epithelial cells of the prostate gland. "The study by Børretzen and colleagues delivers compelling evidence on the prognostic role of epithelial‐to‐mesenchymal transition (EMT) regulators, Twist, Slug (Snai2), and Snail (Snai1), in prostate cancer." (PMID 40891689, 2025). "We evaluate the downstream effects of the Epithelial-to-Mesenchymal Transition (EMT) transcription factors, ZEB1 and SNAI1, and analyze their potential significance as biomarkers for increased aggressiveness and immune response in prostate cancer (PCa)." (PMID 38672562, 2024). "On the other hand, it was revealed that miR-153, the targeting miRNA of SNAI1 and an independent marker for the prognosis of prostate cancer, suppressed cancer cell invasion by targeting the expression of SNAI1." (PMID 38671227, 2024). "Alike ZEB1 also SNAI1 and SNAI2 are strongly associated with high Gleason score 10, indicating them as markers of an aggressive and advanced prostate cancer phenotype." (PMID 29206234, 2017). "One such pathway is the SNAI1/2, which regulate ZEB1/2 expression and have been implicated in prostate cancer." (PMID 21747944, 2011). "It has been reported that inhibition of SNAI1 can induce cellular senescence in prostate cancer and various cell lines, but the relationship between SNAI1 and senescence in PTC remains unclear." (PMID 38329430, 2024). "Furthermore, SNAI1 plays a critical role in the aggressiveness of prostate cancer by increasing the expression of CD44 and vimentin." (PMID 37476073, 2023). "Additionally, in ARCaP prostate cancer cells transfected with Snai1 cDNA to overexpress Snai1, PXDN expression was significantly fold up-regulated compared with control." (PMID 37801286, 2023). "Moreover, EMT-related transcription factors (EMT-TFs), such as TWIST1 (Twist), SNAI1 (Snail), and SNAI2 (Slug) were all required for migration/metastasis and the alteration of these factors was associated with advanced prostate cancer." (PMID 31060254, 2019). "Furthermore, the mRNAs of Skp2, RhoA, and SNAI1 were identified through q-PCR to be decreased in the DT-treated prostate cancer cells." (PMID 28157698, 2017). "According to the contradictory findings, SNAI1 gene expression was higher in gastrointestinal tumor tissue than in normal tissues, and ZEB2 expression was significantly higher in prostate cancer tissue than in BPH tissue." (PMID 40693059, 2025). "Supporting evidence from prostate cancer shows that AR can upregulate EMT-related transcription factors, including Twist-related protein 1 (TWIST1) and zinc finger protein SNAI1 (SNAI1)." (PMID 40940929, 2025). "TGF-β induces the EMT in prostate cancer in vitro via the suppression of E-cadherin levels, and elevates the expression of fibronectin, vimentin, and EMT-TFs such as ZEB1 and SNAI1/2." (PMID 39941895, 2025). "The results showed that the expression levels of CDH2, SNAI1, ZEB1, and ZEB2 were significantly downregulated in prostate cancer compared to controls, while the expression of CDH1 was significantly upregulated." (PMID 40693059, 2025). "In contrast, in a panel of prostate cancer cell lines, PXDN protein levels were found to be higher in cells expressing Snai1 and vimentin." (PMID 37801286, 2023). "In the process of TGFβ1 induced EMT in the prostate cancer cell line DU145, H3K4me3 enrichment and RbBP5 binding increased in the vicinity of the Snail (SNAI1) transcription start site." (PMID 36319643, 2022). "Collectively, these results indicated that there was low expression of CCND1, CDK4 and TWIST1; high expression of SNAI1, SNAI2, and CDH1 was correlated with good prognosis of prostate cancer patients." (PMID 31060254, 2019). "In this study, we found that in the process of TGF-Beta1 induced EMT in the prostate cancer cell line DU145, H3K4me3 enrichment and RbBP5 binding increased in the vicinity of Snail (SNAI1) transcription start site." (PMID 27566588, 2016).
prostate carcinoma (continued). "Furthermore, the KM plotter and GEPIA results demonstrated that when prostate cancer progresses, there are changes in the expression of CDH1, CDH2, VIM, SNAI1, ZEB1, and ZEB2." (PMID 40693059, 2025). "Employing siRNA-based partial target modulation in DU145 and PC3 prostate carcinoma cells, inhibition of EMT-related gene expression (with downregulation of MMP9, MMP2, VIM, and SNAI1, among others) and suppression of migration and metastasis were assessed in vitro." (PMID 32466621, 2020). "While a role for miR-448-3p in prostate cancer has not yet been reported, the seed sequence for miR-448-3p is predicted to target SNAI1, a key EMT-transcription factor." (PMID 31428571, 2019). "This study revealed that EBAG9 modulates the expression of EMT-related genes containing VIM, SNAI1, and SNAI2 in prostate cancer cells, suggesting that EBAG9 could stimulate cancer progression and invasion through EMT pathway." (PMID 29362448, 2018). "Indeed, silencing of GPR137 resulted in a downregulation of SNAI1/SNAIL and SNAI2/SLUG and a corresponding increase in E-cadherin expression in human prostate cancer cells." (PMID 28975893, 2017). "The link between SPINK1 and increasing sphere formation ability in prostate cancer was also validated using the 22RV1 cell line and by regulating the expression of genes involved in stemness and epithelial-mesenchymal transition (EMT), including SNAI1 (SNAIL), SNAI2 (SLUG), and TWIST1." (PMID 33916984, 2021). "For example, in induced pluripotent stem cells (iPSC) and prostate cancer cells, mesenchymal genes, such as ZEB1, ZEB2, CDH2, TWIST and SNAI1/2, are enriched with EZH2 binding, but not epithelial genes such as CDH1 or SNAI3." (PMID 37175580, 2023).
glioma (40 papers, 2013 to 2026). A benign or malignant brain and spinal cord tumor that arises from glial cells (astrocytes, oligodendrocytes, ependymal cells). "However, the biological mechanisms underlying SNAI1 function in gliomas need further investigation." (PMID 24959930, 2014). "In particular, we noted higher expression of the pre-EMT transcription factor SNAI1 in H3K27M-mutant gliomas." (PMID 33319914, 2020). "Certain transcription factors such as Slug, Snai1, Twist and matrix metalloproteinases, have been reported to be implicated in EMT, and to promote glioma cell migration and invasion." (PMID 28851312, 2017). "Sustained elevation of SNAI1 has been suggested to promote a glial-mesenchymal transition in gliomas after radiation." (PMID 26090865, 2015). "SNAI1 depletion by shRNA retarded the cell cycle and suppressed proliferation and invasion in glioma cell lines." (PMID 24959930, 2014). "In our study, we found that reduced SNAI1 expression by shRNA suppressed the cell cycle, proliferation, invasiveness and migration of glioma cell lines." (PMID 24959930, 2014). "We tested the relationship between SNAI1 and miR-128 in glioma cell lines by transfecting SNAI1 shRNA and scramble oligonucleotides into U251 and U87 cells." (PMID 24959930, 2014). "We analysed the CGGA microarray data of 158 glioma tissues using Matlab software to explore the potential relationship between SNAI1 and miRNA expression." (PMID 24959930, 2014). "In our study, the mechanism of how the SNAI1/miR-128/SP1 axis facilitates glioma progression was investigated." (PMID 24959930, 2014). "In general, our data revealed that upregulated SNAI1 accelerates glioma progression and suppresses the expression of miR-128, which can oppose SNAI1's effect and modulate SP1 expression." (PMID 24959930, 2014). "The mRNA and protein expression levels of SNAI1 were detected using normal brain tissues and glioma (WHO grade II to IV) tissues and the results were consistent with the CGGA data." (PMID 24959930, 2014). "The CGGA data showed that SNAI1 was up-regulated in glioma tissues, especially in WHO grade IV gliomas in comparison with normal brain tissues." (PMID 24959930, 2014). "After investigating the Chinese Glioma Genome Atlas (CGGA) data, we found that SNAI1 expression increases in glioma tissues (WHO grade II to IV) in comparison with normal brain." (PMID 24959930, 2014). "Cell cycle, invasion and proliferation were restrained by the application of SNAI1 shRNA in glioma cell lines." (PMID 24959930, 2014). "Our findings first establish a role for the SNAI1/miR-128/SP1 axis in the regulation of glioma evolution." (PMID 24959930, 2014). "In this study, we demonstrate that miR-128b is directly suppressed by SNAI1 by binding to the promoter region of miR-128b in gliomas." (PMID 24959930, 2014). "In the SNAI1/miR-128/SP1 axis, miR-128 acts as a negative regulator, which resist the SNAI1-promoted progression of gliomas." (PMID 24959930, 2014). "In the current study, we demonstrated that miR-128b is a direct target of SNAI1 and showed that miR-128 can override the effect of SNAI1 on glioma cell cycle, proliferation and invasiveness." (PMID 24959930, 2014). "The Chinese Glioma Genome Atlas (CGGA) data revealed that SNAI1 was up-regulated in glioma and we confirmed the findings in normal and glioma tissues." (PMID 24959930, 2014). "The current data suggest that the NF-κB/Snai1 axis may be responsible for IF1-mediated metastasis in glioma." (PMID 26622799, 2015). "In addition, the SNAIL (SNAI1) gene was found to enhance irradiation-induced glioma progression via EMT and glioma stemness." (PMID 25605251, 2015). "Thus, we have expanded the current knowledge by delineating the function of the SNAI1 axis in glioma progression, and propose that this axis is a potential candidate molecular target for clinical prognosis or therapy." (PMID 24959930, 2014). "Primarily, miR-128 ASO antagonised SNAI1 shRNA function in glioma cell lines." (PMID 24959930, 2014).